TFEC (transcription factor EC)
Description:
Transcriptional regulator that acts as a repressor or an activator. Acts as a transcriptional repressor on minimal promoter containing element F (that includes an E-box sequence). Binds to element F in an E-box sequence-specific manner. Acts as a transcriptional transactivator on the proximal promoter region of the tartrate-resistant acid phosphatase (TRAP) E-box containing promoter (By similarity). Collaborates with MITF in target gene activation (By similarity). Acts as a transcriptional repressor on minimal promoter containing mu E3 enhancer sequence (By similarity). Binds to mu E3 DNA sequence of the immunoglobulin heavy-chain gene enhancer (By similarity). Binds DNA in a homo- or heterodimeric form.
Synonyms: TFE-C; bHLHe34; hTFEC-L; TCFEC; TFECL; TFEC-L
Tractability: PROTAC: ubiquitination databases record sites on it.
Gene: Protein-coding gene on chromosome 7 (115,935,148 to 116,159,896, reverse strand). Ensembl gene ENSG00000105967.
Subcellular location: Nucleus
Subcellular location (Human Protein Atlas): Nucleoplasm; Cytosol
Pathways (Reactome):
Developmental Biology: Transcriptional and post-translational regulation of MITF-M expression and activity
Gene Ontology:
Molecular function: DNA-binding transcription repressor activity, RNA polymerase II-specific; protein binding; sequence-specific double-stranded DNA binding; DNA-binding transcription activator activity, RNA polymerase II-specific; DNA-binding transcription factor activity, RNA polymerase II-specific; RNA polymerase II cis-regulatory region sequence-specific DNA binding; protein dimerization activity
Biological process: negative regulation of transcription by RNA polymerase II; positive regulation of transcription by RNA polymerase II; regulation of transcription by RNA polymerase II; regulation of DNA-templated transcription
Cellular component: nucleoplasm; chromatin; nucleus
Genetic constraint (gnomAD): Loss-of-function variants: 18 observed, 29.49 expected, observed/expected ratio (o/e) 0.61, 90% interval 0.42 to 0.9. The upper end of that interval is the gene's LOEUF score, 0.9, which puts it in group 3 of 6, group 1 being the genes least tolerant of losing a copy. Missense variants: 338 observed, 352.67 expected, observed/expected ratio (o/e) 0.96, 90% interval 0.88 to 1.05. Synonymous variants: 118 observed, 125.79 expected, observed/expected ratio (o/e) 0.94, 90% interval 0.81 to 1.09.
Homologues: Orthologues: chimpanzee TFEC (99% identical), macaque TFEC (98% identical), dog TFEC (89% identical), rabbit TFEC (84% identical), guinea pig TFEC (82% identical), pig TFEC (82% identical), rat Tfec (72% identical), mouse Tfec (70% identical), tropical clawed frog tfec (62% identical), zebrafish tfec (54% identical), Drosophila melanogaster Mitf (33% identical), Caenorhabditis elegans hlh-30 (29% identical). Paralogues in human: MITF (47% identical), TFE3 (44% identical), TFEB (41% identical).
Diseases named in the same sentence as TFEC in open-access papers:
TFEC is named in the same sentence as 23 diseases in open-access papers, as found by Europe PMC text mining. Sharing a sentence is not in itself a finding about the gene and the disease. The quoted sentences say what the papers report.
renal cell carcinoma (4 papers, 2016 to 2023). "MiT/TFE proteins, with the exception of TFEC, are involved in the development of renal cell carcinoma (RCC)." (PMID 36672892, 2023).
melanoma (3 papers, 2020 to 2021). A malignant, usually aggressive tumor composed of atypical, neoplastic melanocytes. "Together with microphthalmia-associated transcription factor, transcription factor E3 and transcription factor EC, TFEB belongs to the microphthalmia family of bHLH-leucine zipper transcription factors that may be implicated in human melanomas, renal and pancreatic cancers." (PMID 33252196, 2020). "MITF, TFEB and TFE3 are expressed to some extent across melanoma tumors and cell lines, whereas TFEC is not." (PMID 32881934, 2020).
myocardial infarction (3 papers, 2022 to 2026). Gross necrosis of the myocardium, as a result of interruption of the blood supply to the area, as in coronary thrombosis. "Heart-apoptosis-associated PIWI-interacting RNA (HAAPIR) regulated cardiomyocyte death after myocardial infarction by boosting NAT10-mediated ac4C modification of transcription factor EC (Tfec) mRNA." (PMID 37612540, 2023). "Together, these results suggest that TFEC promotes Bik expression through its direct binding to the promoter region of Bik, and TFEC and Bik are direct downstream molecules of HAAPIR in the regulation of cardiomyocyte apoptosis and myocardial infarction with I/R injury." (PMID 35138696, 2022).
angiomyolipoma (1 paper, 2024). A neoplasm with perivascular epithelioid cell differentiation often associated with tuberous sclerosis. "Indeed, MITF is considered a hallmark gene of lymphangioleiomyomatosis (LAM) and angiomyolipomas in TSC44,45, based on upregulation of genes that are known transcriptional targets of MITF/TFE3/TFEB/TFEC including MelanA and Cathepsin K46,47." (PMID 38195686, 2024).
asthma (1 paper, 2022). "However, several genes are newly implicated in asthma, including Rho GTPase activating protein 15 (Arhgap15), Pleckstrin (Plek), and Transcription factor EC (Tfec)." (PMID 35600600, 2022).
bovine tuberculosis (1 paper, 2025). "TFEC, has been previously identified as a candidate gene for bovine tuberculosis in African zebu cattle." (PMID 40725399, 2025).
cardiac hypertrophy (1 paper, 2025). "Additionally, the transcription factor EC (TFEC), a basic helix-loop-helix transcription factor, contributes to cardiac hypertrophy by inhibiting AMPK-activated signaling pathways within the mTOR axis." (PMID 40002810, 2025).
coronary artery disease (1 paper, 2024). "TFEC is a member of the microphthalmia-associated transcription factor family, which may promote the development of coronary artery disease." (PMID 39896809, 2024).
kidney cancer (1 paper, 2016). Primary or metastatic malignant neoplasm involving the kidney. "Some of the TENET-identified TFs in KIRC (TFEC, RUNX1, ZNF395) have been previously linked to kidney cancer." (PMID 27833659, 2016).
lung carcinoma (1 paper, 2013). "As for TFEC, we have found association with higher expression of this gene and improved lung cancer survival." (PMID 24349289, 2013).
ovarian carcinoma (1 paper, 2022). A malignant neoplasm originating from the surface ovarian epithelium. "A recent study reports that TFEC is expressed at higher levels in ovarian cancer tissues, compared to normal tissues, and correlates with malignant progression and poor survival for ovarian cancer patients." (PMID 35665902, 2022).
cancer (10 papers, 2019 to 2025). A tumor composed of atypical neoplastic, often pleomorphic cells that invade other tissues. "We further integrated our methylation results with RNA-seq data, and we identified 11 genes, including six related to immune functions (AHR, LRFN5, NTRK2, RSPO2, SAMSN1, and TFEC), and three related to cancer (SLC12A5, SORCS1, and TP63)." (PMID 39795948, 2024). "It belongs to the bHLH-leucine zipper transcription factor microphthalmia family, which includes microphthalmia-associated transcription factor, transcription factor E3 and transcription factor EC, and is known to be deregulated in cancer." (PMID 33912071, 2021). "The role of TFEC in cancer progression has been studied to a limited extent; thus, to further explore the biological functions in which TFEC may be involved, TFEC‐coexpressed molecules in the cBioPortal database were elucidated." (PMID 33278864, 2021). "Furthermore, for many of these TFs, such as TFEC, IRF5, and ERF, we found a significant association between TF expression and cancer prognosis using TCGA data, suggesting that the dysregulation of these TFs can also impact cancer outcomes." (PMID 39013578, 2024). "TFEC is a member of the microphthalmia (MiT) family, which regulates multiple physiological processes, including cell survival, differentiation, proliferation, invasion, metabolism, and DNA damage repair, thus contributing to the initiation and development of some cancer types." (PMID 34557425, 2021). "Transcription factor EC (TFEC) regulates a variety of cytokines capable of cancer stem cell promotion, while the pro-cancer or anti-cancer role of Epstein-Barr virus-induced gene 3 (EBI3) is less clearly understood." (PMID 38674080, 2024). "TFs associated with PIK3CA mutations were involved in WNT signaling, epithelial–mesenchymal transition, and cancer stem cell transition, including ELF3, TFEC, STAT4, STAT5B, NFATC1, GLIS1, CDC5L and AR." (PMID 36243974, 2022).
infection (2 papers, 2023 to 2025). The state of being infected such as from the introduction of a foreign agent such as serum, vaccine, antigenic substance or organism. "TFEC has also been identified as a Hub gene and is differentially expressed for infection of BRSV and IBR among beef cattle." (PMID 40725399, 2025). "Moreover, we revealed a bipolar mode of fibroblast differentiation and put forward the hypothesis that infection could modulate fibroblast toward a pro-inflammatory phenotype through NPAS2 and TFEC." (PMID 36927352, 2023).
tumor (2 papers, 2017 to 2024). "The regulon specificity score (RSS) highlighted unique regulons across the three studied regions, with MITF(+), PRDM1(+), MAX(+), TFEC(+), and BHLHE41(+) emerging as the most specific regulons within the tumor core." (PMID 38938448, 2024).
head and neck tumors (1 paper, 2019). "Among the most impressive differences in TF activity, head and neck tumors display lower activities of FEV, TFAP2B and GATA2 and higher activities of TFEC, LEF1, and MAFB compared to SDHD-null tumors of other anatomical locations." (PMID 31234811, 2019).
kidney disease (1 paper, 2024). "The other members of the TFEB family (TFE3, MITF, and TFEC) may impact TSC-associated kidney disease and other manifestations of TSC, via similar mechanisms." (PMID 38195686, 2024).
TFEC also shares sentences with these, for which no sentence is quoted: clear cell renal carcinoma (1 paper); lymphangioleiomyomatosis (1); neuroblastoma (1); osteosarcoma (1); pancreatic cancers (1); sarcoma (1); viral infection (1).